BRCA2 (BRCA2 DNA repair associated)
Diseases named in the same sentence as BRCA2 in open-access papers (continued):
Sharing a sentence is not in itself a finding about the gene and the disease.
tumor (continued). "BRCA2 mutations occur in 5–10% of prostate cases, and RAD51C/RAD51D, BRIP1, or BARD1 defects may broaden eligibility across tumor types." (PMID 40864792, 2025). "BRCA2 is a tumor suppressor essential for maintaining genomic stability." (PMID 41162355, 2025). "Given the complexity of HRD biomarkers, key assay features include the selection of HRR genes (BRCA1, BRCA2, PALB2, RAD51C, RAD51D), definitions of genomic scars (LOH, TAI, LST), mutational signatures analyzed, use of comparator samples, and tumor-specific HRD score calculations." (PMID 40864792, 2025). "Two patients with BRCA mutations (one somatic BRCA1/2 and one germline BRCA2) showed no tumor response." (PMID 40743286, 2025). "Analysis of one matched primary tumor confirmed the same BRCA2 methylation." (PMID 39392573, 2025). "Simultaneously, tumor organoids derived from the PDX model from the first patient with pleural TNBC metastasis with BRCA2 methylation were treated with two different PARP inhibitors (Olaparib and Rucaparib) in three different concentrations (25, 50 and 100 μM)." (PMID 39392573, 2025). "The BRCA2 P/LPGVs in brain, uterine, and upper GI malignancy are unexpected with these tumor types." (PMID 41465149, 2025). "We showed that loss of function events in BRCA1/2 comprising missense‐ and frameshift mutations, CN‐losses, as well as inactivating BRCA2 gene fusions can be associated with an elevated GIS independent of the respective tumor entity." (PMID 40278800, 2025). "We speculate that chronic APOBEC3 activity in long-established BRCA2 tumor lines like PEO1 may have led to compensatory changes or selection of downstream effectors that can help these cells bypass APOBEC3-induced DNA damage." (PMID 41162355, 2025). "However, we found that tumor mutation burden and predicted neoantigen counts were equivalent in BRCA1-deficient and BRCA2-deficient tumors between STS and LTS groups." (PMID 41255967, 2025). "BRCA1 and BRCA2 are two tumour suppressor genes that play a role in DNA repair processes." (PMID 40844552, 2025). "Additionally, we compared BC xenografts with an identified BRCA methylation to their matched primary tumors and subsequently investigated the efficacy of PARP inhibitors on tumor organoids from a BRCA2 promoter-methylated BC." (PMID 39392573, 2025). "The comparative Next-Generation Sequencing (NGS) analysis between normal tissue and the two distinct tumor areas (A1 and A2) revealed relevant molecular features other than the loss of heterozygosity (LOH) of BRCA2 gene and the 3p21.31 chromosomal sub-band where the MLH1 gene is located." (PMID 40076915, 2025). "We extended these findings to BRCA2 mutant tumor lines, PEO1 (ovarian) and CAPAN1 (pancreatic)." (PMID 41162355, 2025). "BRCA1 and BRCA2 are two critical tumor suppressor genes crucial for DNA double-strand break repair." (PMID 39987121, 2025). "None of the tumors demonstrating tumor regression had a BRCA1 or BRCA2 gene mutation likely to result in loss of function." (PMID 41145467, 2025). "However, 2 patients with both BRCA2 and either FANCD2 or FANCE germline deleterious variants also had complex genomic tumor profiles with numerous copy number gains, losses, and copy-neutral LOH (CN-LOH) events." (PMID 40072012, 2025).
tumor (continued). "Additionally, in our cohort of iCCA patients treated with cisplatin, we noted a significant increase in BRCA2 expression in chemotherapy‐resistant tumours compared to those sensitive to chemotherapy." (PMID 38773866, 2024). "As proven in the present study, the list of genes from the 44-gene panel more frequently mutated in BOT compared to the other tumor groups (FANCB, SEM1, FANCA, BRCA2, CHEK2, MUTYH, RAD50) was much longer than analogically altered genes in the hot-spot panel (KRAS only)." (PMID 39456660, 2024). "As BRCA1/BRCA2 proteins are responsible for the repair of double-strand DNA breaks (DSBs), the presence of pathogenic variants in BRCA2 leads to the impaired activity of its protein product and thus increases the risk of a DSB in a tumor cell." (PMID 39456660, 2024). "More recently, 3E10 was found to bind RAD51 and to be synthetically lethal in BRCA2- and PTEN-deficient cells, and new pre-clinical studies have also demonstrated the ability of 3E10 to deliver nucleic acids into tumor cells (with functional release) following systemic administration." (PMID 39352803, 2024). "Therefore, they act as tumor suppressor genes, as mutations have been observed in tumor cells due to genomic instability, and approximately 80% of BRCA1 and 3–17% of BRCA2-related BC belong to the TNBC subtype." (PMID 38892472, 2024). "BRCA1 and BRCA2 (BRCA) are two of the important tumor suppressor genes." (PMID 38671360, 2024). "Yet, when only high-impact variants were considered, BRCA1 (but not BRCA2) was, as expected, more frequently altered in hgOvCa in comparison with all the remaining tumor groups." (PMID 39456660, 2024). "When the subgroups of women with a germline BRCA1 and BRCA2 PV were analysed separately, there was a trend towards a significantly greater proportion of tumours with CRS3 in the germline BRCA2 PV subgroup compared to the germline BRCA1/2 wild type group (OR 2.13, 95% CI 0.95–4.91; P = 0.0647)." (PMID 39550490, 2024). "Importantly, our in vivo studies indicate that while a-Egfl6 therapy improved response to a-PD-L1 therapy in both the 2F8c (s.c.)tumor model and the ID8p53–/– Brca2–/– (i.p.)model, it was more efficacious in the immune hot 2F8c tumor model." (PMID 39312740, 2024). "Here, we hypothesize that the necessary genetic modifications for oncogenesis in the context of BRCA1/BRCA2 inactivation may arise from recurrent copy number alterations (CNAs) present in these neoplasms." (PMID 39198848, 2024). "ER positivity in BRCA2-mutated BC was strongly associated with lymph node metastasis and tumor diameter but not with pathological grade." (PMID 38184581, 2024). "Notably, BRCA1 and BRCA2 stand as tumor-suppressor genes essential to the preservation of genomic integrity through the mending of dsDNA lesions employing homologous recombination (HR)." (PMID 38397209, 2024). "BRCA1 and BRCA2 mutations are the pathogenic variants of BRCA that cause loss of function in BRCA1/2 genes and result in genomic instability and tumor development, which might have been the case in our patient." (PMID 39156267, 2024).
tumor (continued). "Notably, the somatic NGS panel can offer other information with clinical relevance, such as the presence of mutations in BRCA1, BRCA2, PALB2, ERBB2, and ESR1, in addition to molecular changes that can be treated with tumor-agnostic therapies." (PMID 38952553, 2024). "Based on the obtained correlation data, we hypothesized that MIR503HG influences the BRCA2 gene expression, thereby modulating DNA repair mechanisms and mediating the tumor-promoting effects." (PMID 39676172, 2024). "Tissue NGS (Tempus xT 648 gene panel) was obtained in week 81, revealing a BRCA2 copy number loss (unknown whether biallelic or monoallelic), TP54 frameshift mutation, RB1 and TOP2A mutations, with a high tumor mutation burden (TMB) of 10 m/MB." (PMID 39666931, 2024). "This term denotes a phenocopy of BRCA1 or BRCA2 variants, a situation in which an HRR defect exists in a tumor in the absence of germline BRCA1 or BRCA2 changes." (PMID 38397209, 2024). "It was recently shown that BRCA2 PVs may affect the tumor microenvironment differently than BRCA1 PVs, and that BRCA2-associated tumors might respond better to checkpoint blockade immunotherapy." (PMID 38339330, 2024). "Although the protein abundance severely decreased, the mRNA level of BRCA2 dramatically increased in tumor samples compared with normal samples, which indicates that the downregulation of the BRCA2 protein level was triggered by post-translational modification." (PMID 39062881, 2024). "The simultaneous analysis of tumor and germline samples allowed the identification of somatic variants present in low frequency (<10%), and the detection of LOH in tumors from six patients with germline pathogenic/likely pathogenic variants in BRCA1 or BRCA2." (PMID 38308422, 2024). "Indeed, Al Knudson in the 1970s had proposed that both copies of tumour-preventing genes like BRCA2 must be inactivated to initiate carcinogenesis." (PMID 39711301, 2024). "BRCA2 downregulation may reflect reduced tumor suppressor function in the unfavorable pediatric AML clusters." (PMID 36982970, 2023). "Following SEALigHTS validation for BRCA1 and BRCA2, our hypothesis was tested using an independent research set of 95 pairs from tumor and adjacent normal breast tissues." (PMID 37046838, 2023). "BRCA2 mediates the recruitment of the recombinase to DNA double strand breaks, which is not only essential for homologous recombination but is also responsible for the tumour’s suppressive function of this repair process." (PMID 37644384, 2023). "Furthermore, tumours showing homologous recombination deficiency, due to loss of BRCA1, BRCA2, PALB2 and CHEK2 function, have been shown to be especially sensitive to platinum-based chemotherapeutics and PARP inhibition." (PMID 36831687, 2023). "Hence, both treatment groups exhibited reduced tumor volumes, which implied importance of BRCA1 and BRCA2 proteins as tumor suppressors p play role on tumor volume reduction." (PMID 36631481, 2023). "We performed all analyses separately for the ER-negative and ER-positive patient groups, corresponding to the specific PREDICT models for ER-negative and ER-positive breast cancer and the characteristic tumor phenotypes of the BRCA1 and BRCA2 variant carriers, respectively." (PMID 37173335, 2023). "Somatic BRCA2 LOH was detected in the tumor samples from this patient." (PMID 37087482, 2023). "In addition, both tumor cohorts with poor and good responses to neoadjuvant treatment presented mutations in ARID1A, CREBBP, BRCA2 and RAD50, although with significantly different frequencies." (PMID 37373240, 2023). "As for the loss of BRCA2, the model for loss of BRCA1 loss in ovary had sufficient predictive power (PR-AUC-E = 0.3) in the other data set, suggesting that the model works independently of the metastatic capacity of the tumour." (PMID 36883553, 2023). "In addition to its function in the DNA repair mechanism, BRCA2 inhibits tumor development by acting as a tumor suppressor." (PMID 37509303, 2023).
tumor (continued). "Their study population of non-BRCA1/BRCA2 tumours had a similar sample size to our study." (PMID 37316882, 2023). "One tumor harbored a CDKN2A homozygous deletion and one tumor had an oncogenic BRCA2 alteration." (PMID 38143440, 2023). "However, in the ER+ stratum, BRCA2-carriers had a higher proportion of tumor grade 3 than the other two groups." (PMID 38036573, 2023). "Although there was not statistically differences between BRCA1 c.5309G>T carriers group and BRCA2 c.1310_1313delAAGA carriers group in terms of tumor laterality, histopathological subtype, tumor grade, RE and RP expression, we detected proportional differences between patients groups." (PMID 37055759, 2023). "Furthermore, knockdown of BRCA2 after cisplatin treatment also decreased the metastasis of tumours, in vivo." (PMID 37113717, 2023). "We first assessed the effect of ART558, alone and in combination with IR, in three tumor cell lines that do not harbor mutations in BRCA-1 or BRCA-2 genes: HCT116 (colorectal), H460 (lung), and T24 (bladder)." (PMID 36689546, 2023). "In addition, a germline BRCA2 Exon 14–16 deletion was reported in tumour DNA from another patient in our study, confirming the ability of the myChoice® CDx to detect this pathogenic large rearrangement." (PMID 38201604, 2023). "Additionally, BRCA2 + NP treated mice showed lesser tumor volume than the control (~ 241 mm3 vs. 485 mm3, p < 0.05)." (PMID 36631481, 2023). "In addition, we demonstrated that the tumor weight in BRCA2 + NP treated mice was also reduced (0.4332 g vs. 1.172 g, p < 0.05)." (PMID 36631481, 2023). "From a total of 6830 tumor samples from 6527 individual patients that underwent tumor DNA sequencing, 584 unique tumor variants were identified in the gene list of interest (ATM, BRCA1, BRCA2, MLH1, MSH1, MSH6, PALB2 and PMS2) from 503 unique tumor samples/patients during the study period." (PMID 36261688, 2023). "A detailed analysis of the TME revealed that olaparib monotherapy resulted in a large number of immunosuppressive and immunomodulatory effects in the more inflamed Brca1-deficient TME but not Brca2-deficient tumours." (PMID 38017453, 2023). "Earlier work also suggests that germline BRCA1 and BRCA2 pathogenic variants are unlikely to be found in patients with tumours of mucinous histology (0 to 4%)." (PMID 37076566, 2023). "The BRCA2 gene is a known tumor suppressor contributing to DNA repair." (PMID 37101120, 2023). "Moreover, for BRCA1 mutation carriers, nFTH1 expression in the tumor was associated with smaller tumor size (p = 0.045) and positive HER2 status (p = 0.049), while in BRCA2 mutation carriers, nFTH1 expression was associated with positive ER status (p = 0.004)." (PMID 38201455, 2023). "All objective responses in this trial were in tumours harbouring BRCA2, ATM or CHEK2 alterations." (PMID 37365284, 2023). "Finally, in in vivo experiments, curcumin sensitized BRCA2-knockout MCF-7 cells to CPT-11 chemotherapy in tumor xenografts." (PMID 36980703, 2023). "DACH1 deletion co-occurred with deletion of BRCA2, consistent with TCGA analysis demonstrating multiple pathways may be disrupted in a given tumor type." (PMID 37095257, 2023). "BRCA2 is a tumor suppressor gene that plays a crucial role in homologous recombination (HR) repair." (PMID 36533385, 2023). "This is consistent with the OC-predisposing genes BRCA1 and BRCA2, where loss of the wild-type allele is not always observed in tumour cells from carriers of pathogenic variants in these CPGs." (PMID 36833203, 2023).
tumor (continued). "Triple negative tumour was observed only in one patient harboring a BRCA2 VUS." (PMID 37277882, 2023). "To resolve this aspect of reciprocal pairs, we performed linked-read (LR) and standard WGS on 46 tumours and matched normal samples that were originally found by clinical panel sequencing to have inherited or somatic mutations in BRCA1 (27 cases) or BRCA2 (19 cases)." (PMID 37587346, 2023). "Of 60 evaluable patients, 58 (97%) exhibited ≥1 BRCA1 or BRCA2 pathogenic tumor mutation (tBRCA1/2mut); no patients had both BRCA1 and BRCA2 mutations." (PMID 37803017, 2023). "BRCA2 suppresses tumor formation by potentiating DNA repair via homologous recombination." (PMID 36976771, 2023). "Sensitivity to either GSK3326595 or niraparib did not correlate with BRCA1 or BRCA2 mutation status or tumor type." (PMID 37596538, 2023). "Indeed, in a BRCA2-mutated prostate cancer xenograft model, PSMA-TTC plus the PARP inhibitor olaparib showed more notable anti-tumor activity than PSMA-TTC alone, while olaparib alone showed no activity." (PMID 36726355, 2022). "Consistently, immunohistochemical (IHC) analyses revealed that BRCA2‐deficient, but not BRCA2‐proficient, tumours exhibited increased level of the DNA damage marker γH2AX upon exposure to either pyridostatin or talazoparib." (PMID 35107878, 2022). "The tumor also showed BRCA2 isoform switching and a MYC amplification." (PMID 36344544, 2022). "The tumor suppressors BRCA1 and BRCA2 have also been implicated in R-loop metabolism." (PMID 36002001, 2022). "Moreover, the correlation between tumor size and lymph node involvement in BRCA1 mutation carriers has been reported to be weaker than for sporadic BC or BRCA2-associated BC." (PMID 35507134, 2022). "According to the Knudson hypothesis, also known as the two-hit hypothesis, in the case of most tumor-suppressor genes (such as BRCA1 and BRCA2), both alleles need to be inactivated to cause a phenotypic change." (PMID 35626055, 2022). "Tumor M273 harbored a germline BRCA2 mutation (c.3847_3848delGT p.Val1283fs) without loss of the other allele (mono-allelic)." (PMID 35662281, 2022). "BRCA1 mutation carriers more often had a larger tumor than BRCA2 mutation carriers (pT1c 71.6% vs 63.3%, p = 0.030, data not shown) and more often had an ER-negative tumor (79.7% vs 26.4%, p < 0.001, data not shown)." (PMID 35507134, 2022). "The recurrent tumor had allele-specific LOH and a BRCA2 isoform switch." (PMID 36344544, 2022). "One RECAP-HRP tumor (M273) harbored a germline BRCA2 mutation (c.3847_3848delGT p.Val1283fs) without loss of the other allele (mono-allelic)." (PMID 35662281, 2022). "BRCA2 is a tumor suppressor and a key mediator of homologous recombination (HR) in vertebrates." (PMID 36090173, 2022). "Other mutations in the tumor-suppressor genes, such as INK4A, LKB1, and BRCA2, are common." (PMID 36556296, 2022). "The HRD tumor with mono-allelic pathogenic germline BRCA2 mutation (M273) was not identified by the other tests." (PMID 35662281, 2022). "Based on clinical germline or tumor testing performed prior to enrollment, 19 patients had a germline BRCA1 (n = 6) or BRCA2 (n = 13) mutation, and 1 had a germline PALB2 mutation; 2 patients had a BRCA2 variant of uncertain significance (VUS) and 1 patient had a PALB2 VUS." (PMID 35750695, 2022). "In addition, the mice model with the BRCA2−/− xenograft showed decrease of the tumor growth after first eight days of inhibitor administration, compared to vehicle." (PMID 36613762, 2022). "This indicates that if the patient exhibits tumor recurrence and metastasis in future follow-up, targeted BRCA2 therapy may be used." (PMID 35912179, 2022). "This suggested that the DNA damage inflicted by pyridostatin, which underlies its toxicity against these tumours, can be repaired in the absence of BRCA2." (PMID 35107878, 2022).